UQCRHL (ubiquinol-cytochrome c reductase hinge protein like)
Description:
May be a component of the ubiquinol-cytochrome c reductase complex (complex III or cytochrome b-c1 complex), which is part of the mitochondrial respiratory chain. This protein may mediate formation of the complex between cytochromes c and c1.
Synonyms: hCG25371
Gene: Protein-coding gene on chromosome 1 (15,807,169 to 15,809,348, reverse strand). Ensembl gene ENSG00000233954.
Subcellular location: Mitochondrion inner membrane
Pathways (Reactome):
Metabolism: Complex III assembly
Gene Ontology:
Biological process: mitochondrial electron transport, ubiquinol to cytochrome c
Cellular component: mitochondrion; mitochondrial inner membrane; respiratory chain complex III; membrane; respiratory chain complex
Genetic constraint (gnomAD): Loss-of-function variants: 3 observed, 6.31 expected, observed/expected ratio (o/e) 0.48, 90% interval 0.22 to 1.22. That is too few expected variants to judge how well the gene tolerates losing a copy. Missense variants: 114 observed, 112.61 expected, observed/expected ratio (o/e) 1.01, 90% interval 0.87 to 1.18. Synonymous variants: 46 observed, 46.12 expected, observed/expected ratio (o/e) 1, 90% interval 0.79 to 1.27.
Homologues: Orthologues: chimpanzee UQCRHL (97% identical), dog UQCRH (91% identical), mouse Uqcrh (87% identical), rat Uqcrh (80% identical), zebrafish uqcrh (66% identical), Drosophila melanogaster UQCR-11L (35% identical), Drosophila melanogaster UQCR-11 (34% identical). Paralogues in human: UQCRH (97% identical).
Diseases named in the same sentence as UQCRHL in open-access papers:
UQCRHL is named in the same sentence as 3 diseases in open-access papers, as found by Europe PMC text mining. Sharing a sentence is not in itself a finding about the gene and the disease. The quoted sentences say what the papers report.
breast carcinoma (1 paper, 2018). "In addition, recurrent amplification-specific genetic features were identified, including genetic variants in the HIST1H1E and UQCRHL genes and fusion transcripts containing MALAT1 non-coding RNA, which is known to be a prognostic indicator for breast cancer and stimulated by estrogen." (PMID 29844878, 2018).
hepatocellular carcinoma (1 paper, 2018). A malignant tumor that arises from hepatocytes. "HIST1H1E is a linker histone gene that may play a role in epigenetic regulation, whereas UQCRHL has been identified as a prognostic factor for hepatocellular carcinoma that plays a pivotal role in mitochondrial respiration." (PMID 29844878, 2018).
tumor (1 paper, 2022). "The tumor-associated significance of the other seven genes (HIST2H2AA4, UQCRHL, AC008269.1, RAB6D, APOL4, HIST1H2AI, ANKAR, SGMS1) remains unclear." (PMID 35480120, 2022).